OR52A4P (olfactory receptor family 52 subfamily A member 4 pseudogene)
Description:
Odorant receptor.
Synonyms: OR52A4
Gene: Transcribed unprocessed pseudogene on chromosome 11 (5,120,621 to 5,121,578, reverse strand). Ensembl gene ENSG00000205494.
Subcellular location: Cell membrane